SUPT16H (SPT16 homolog, facilitates chromatin remodeling subunit)
Description:
Component of the FACT complex, a general chromatin factor that acts to reorganize nucleosomes. The FACT complex is involved in multiple processes that require DNA as a template such as mRNA elongation, DNA replication and DNA repair. During transcription elongation the FACT complex acts as a histone chaperone that both destabilizes and restores nucleosomal structure. It facilitates the passage of RNA polymerase II and transcription by promoting the dissociation of one histone H2A-H2B dimer from the nucleosome, then subsequently promotes the reestablishment of the nucleosome following the passage of RNA polymerase II.
Synonyms: FACTP140; FACT; SPT16/CDC68; FLJ14010; FLJ10857; CDC68; NEDDFAC; SPT16
Tractability: PROTAC: UniProt records ubiquitination sites on it; ubiquitination databases record sites on it; its protein half-life has been measured.
Gene: Protein-coding gene on chromosome 14 (21,351,472 to 21,384,042, reverse strand). Ensembl gene ENSG00000092201.
Subcellular location: Nucleus; Chromosome
Subcellular location (Human Protein Atlas): Nucleoplasm; Nucleoli fibrillar center
Pathways (Reactome):
Disease: Formation of HIV elongation complex in the absence of HIV Tat; Formation of HIV-1 elongation complex containing HIV-1 Tat; HIV elongation arrest and recovery; Pausing and recovery of HIV elongation; Pausing and recovery of Tat-mediated HIV elongation; Tat-mediated HIV elongation arrest and recovery; Tat-mediated elongation of the HIV-1 transcript
Gene expression (Transcription): Formation of RNA Pol II elongation complex; RNA Polymerase II Pre-transcription Events; RNA Polymerase II Transcription Elongation
Chromatin organization: CHD1 and CHD2 subfamily
Gene Ontology:
Molecular function: H2A-H2B histone complex chaperone activity; protein binding; RNA binding; nucleosome binding
Biological process: nucleosome disassembly; transcription elongation-coupled chromatin remodeling; nucleosome assembly; positive regulation of DNA-templated transcription, elongation; regulation of DNA-templated transcription elongation; transcription by RNA polymerase II; nucleosome organization
Cellular component: FACT complex; nucleoplasm; nucleus; chromosome
Genetic constraint (gnomAD): Loss-of-function variants: 23 observed, 133.04 expected, observed/expected ratio (o/e) 0.17, 90% interval 0.12 to 0.25. The upper end of that interval is the gene's LOEUF score, 0.25, which puts it in group 1 of 6, group 1 being the genes least tolerant of losing a copy. Missense variants: 613 observed, 1,308.9 expected, observed/expected ratio (o/e) 0.47, 90% interval 0.44 to 0.5. Synonymous variants: 413 observed, 444.86 expected, observed/expected ratio (o/e) 0.93, 90% interval 0.86 to 1.01.
Homologues: Orthologues: chimpanzee SUPT16H (100% identical), macaque SUPT16H (100% identical), pig SUPT16H (99% identical), dog SUPT16H (99% identical), rabbit SUPT16H (99% identical), rat Supt16h (99% identical), mouse Supt16 (99% identical), tropical clawed frog supt16h (88% identical), guinea pig SUPT16H (84% identical), zebrafish supt16h (84% identical), Drosophila melanogaster dre4 (60% identical), Caenorhabditis elegans spt-16 (47% identical).
Diseases named in the same sentence as SUPT16H in open-access papers:
SUPT16H is named in the same sentence as 18 diseases in open-access papers, as found by Europe PMC text mining. Sharing a sentence is not in itself a finding about the gene and the disease. The quoted sentences say what the papers report.
Intellectual disability (4 papers, 2023 to 2025). "Defects in the FAcilitates Chromatin Transcription (FACT) complex, a histone chaperone composed of SSRP1 and SUPT16H, are implicated in intellectual disability." (PMID 38719542, 2024). "De novo Supt16H missense variants have been identified in neurodevelopmental disorder patients, resulting in autistic features, minor dysmorphic features, intellectual disability, and seizures." (PMID 36769360, 2023). "More interestingly, de novo missense variants in Supt16H that cause intellectual disability, autistic features, minor dysmorphic features, and seizures have been identified in patients with NDDs." (PMID 36769360, 2023). "Similarly, de novo variants in SUPT16H have been shown to play a role in a variety of symptoms in patients, such as intellectual disability, autistic features, precocious puberty, sleeping difficulties, and seizures." (PMID 40984926, 2025).
breast carcinoma (2 papers, 2023 to 2025). "Similar to PRMT5 and APE1, the downregulation of SUPT16H significantly sensitized a breast cancer cell line MCF7 to IR." (PMID 37887269, 2023). "In the CBD signaling, the key axis was formed by SUPT16H, SETD2, and H2BC12, which suggests epigenetic regulation by CBD in the restoration of an epithelial phenotype of breast cancer cells, providing new targets for anticancer therapy." (PMID 40429863, 2025).
developmental delay (2 papers, 2018 to 2025). "CNV deletions affecting CHD8 and SUPT16H were initially described in children with developmental delay and dysmorphic features." (PMID 29693535, 2018).
tongue cancer (1 paper, 2019). A malignant neoplasm affecting the tongue. "Differential expression profiling of the tongue cancer cohort triaged based on the stage, pathology identified multiple candidate markers; JAM2, SMURF1, LY6E, MFN1 and SUPT16H." (PMID 31310629, 2019).
tumor (8 papers, 2011 to 2024). "In this research, we demonstrated that FACT is a potential therapeutic target for B-NHL, and both SSRP1 and SUPT16H are significantly overexpressed in DLBCL tumor tissues and are closely related." (PMID 36691066, 2023). "For example, the facilitates chromatin transcription complex (FACT), which consists of the histone chaperones SUPT16H and SSRP1, has been proven to be remarkably upregulated and contribute to tumor progression by promoting oxidative stress adaptation in HCC10." (PMID 38561384, 2024).
cancer (7 papers, 2011 to 2025). A tumor composed of atypical neoplastic, often pleomorphic cells that invade other tissues. "Along with epigenetic modifiers that were previously implicated in cancer cell fitness, such as CHD1, CHD4, DNMT3B, ELP3, SUPT16H, SUV39H2; novel hits ASH2L, RBX1 and SSRP1 were discovered as essential genes for both U373 and T98G cells suggesting common regulatory role." (PMID 37974198, 2023). "We also discovered that DPM is a FACT-dependent cancer with overexpression of both subunits structure-specific recognition protein 1 (SSRP1), a poor prognosis indicator, and suppressor of Ty 16 (SUPT16H)." (PMID 37974213, 2023).
infection (5 papers, 2017 to 2025). The state of being infected such as from the introduction of a foreign agent such as serum, vaccine, antigenic substance or organism. "Additionally, SUPT16H and SSRP1, another FACT subunit, are both upregulated by EBV during initial infection." (PMID 34572593, 2021).
neurodevelopmental disorder (2 papers, 2024 to 2025). A behavioral and cognitive disorder with onset during the developmental period that involves impaired or aberrant development of intellectual, motor, or social functions. "Pathogenic variants in the CHD8 gene alone have been found in patients with ASD, and pathogenic variants in SUPT16H alone cause a variable-expressed neurodevelopmental disorder." (PMID 40984926, 2025). "In a clinical whole-exome sequencing study focusing on neurodevelopmental disorders, four patients with de novo missense variants of SUPT16H and one patient with a de novo deletion of SUPT16H were identified." (PMID 38719542, 2024). "An ultrarare neurodevelopmental disorder, 14q11.2 microduplication syndrome involves the SUPT16H and CHD8 genes." (PMID 40984926, 2025).
immune disorders (1 paper, 2021). "Our results showed a panel of three downregulated miRNAs (hsa-miR-4516, hsa-miR-494-3p and hsa-miR-542-3p) involved in the regulation of genes associated with viral latency (SUPT16H, TFPI), HIV reactivation (PIM1) and persistent metabolic and immune disorders (ZADH2, CCL16)." (PMID 34829855, 2021).
SUPT16H also shares sentences with these, for which no sentence is quoted: lung carcinoma (2 papers); neuroblastoma (2); Alpha-thalassemia (1); Anxiety (1); depression (1); epilepsy (1); glioblastoma (1); Obesity (1); virus infections (1).